SLC39A5 (solute carrier family 39 member 5)
Description:
Uniporter that transports zinc(2+) into polarized cells of enterocytes, pancreatic acinar and endoderm cells across the basolateral membrane and participates, notably, in zinc excretion from the intestine by the uptake of zinc from the blood into the intestine (By similarity). The transport mechanism is temperature- and concentration-dependent and saturable (By similarity). In addition, is also a high affinity copper transporter in vitro. Also may regulate glucose-stimulated insulin secretion (GSIS) in islets primarily through the zinc-activated SIRT1-PPARGC1A axis (By similarity). Could regulate the BMP/TGF-beta (bone morphogenetic protein/transforming growth factor-beta) signaling pathway and modulates extracellular matrix (ECM) proteins of the sclera. Plays a role in eye development.
Synonyms: ZIP5; LZT-Hs7; MYP24
Tractability: Small molecule: a structure with a bound ligand is known. Antibody: UniProt places it where antibodies can reach, with medium confidence; UniProt predicts a signal peptide or a membrane-spanning region; its Gene Ontology location is reachable by antibodies, with medium confidence.
Gene: Protein-coding gene on chromosome 12 (56,230,039 to 56,238,214, forward strand). Ensembl gene ENSG00000139540.
Subcellular location: Basolateral cell membrane
Subcellular location (Human Protein Atlas): Vesicles; Nucleoplasm
Pathways (Reactome):
Transport of small molecules: Zinc influx into cells by the SLC39 gene family
Gene Ontology:
Molecular function: monoatomic cation:bicarbonate symporter activity; zinc ion transmembrane transporter activity; metal ion transmembrane transporter activity
Biological process: BMP signaling pathway; eye development; G1 to G0 transition involved in cell differentiation; intracellular monoatomic cation homeostasis; neural precursor cell proliferation; zinc ion import across plasma membrane; zinc ion transmembrane transport; zinc ion transport; bicarbonate transport; metal ion transport; transmembrane transport
Cellular component: extracellular exosome; basolateral plasma membrane; plasma membrane; membrane
Genetic constraint (gnomAD): Loss-of-function variants: 42 observed, 49.23 expected, observed/expected ratio (o/e) 0.85, 90% interval 0.67 to 1.1. The upper end of that interval is the gene's LOEUF score, 1.1, which puts it in group 4 of 6, group 1 being the genes least tolerant of losing a copy. Missense variants: 677 observed, 694.37 expected, observed/expected ratio (o/e) 0.97, 90% interval 0.92 to 1.04. Synonymous variants: 311 observed, 327.51 expected, observed/expected ratio (o/e) 0.95, 90% interval 0.87 to 1.04.
Homologues: Orthologues: chimpanzee SLC39A5 (99% identical), macaque SLC39A5 (98% identical), pig SLC39A5 (86% identical), mouse Slc39a5 (84% identical), dog SLC39A5 (83% identical), guinea pig SLC39A5 (83% identical), rat Slc39a5 (83% identical), rabbit SLC39A5 (79% identical), tropical clawed frog slc39a5 (43% identical), zebrafish slc39a5 (39% identical), Drosophila melanogaster Zip71B (29% identical), Caenorhabditis elegans zipt-15 (17% identical). Paralogues in human: SLC39A10 (36% identical), SLC39A6 (31% identical), SLC39A4 (28% identical), SLC39A12 (24% identical), SLC39A14 (22% identical), SLC39A8 (22% identical).
Diseases named in the same sentence as SLC39A5 in open-access papers:
SLC39A5 is named in the same sentence as 39 diseases in open-access papers, as found by Europe PMC text mining. Sharing a sentence is not in itself a finding about the gene and the disease. The quoted sentences say what the papers report.
myopia (9 papers, 2016 to 2025). "Our findings further expand the variants spectrum of SLC39A5 in early-onset high myopia." (PMID 40920702, 2025). "In summary, our data suggest that depletion of SLC39A5 induces zinc deficiency, which restrains TGF‐β signalling–mediated ECM synthesis, thus possibly contributing to high myopia pathogenesis." (PMID 34302427, 2021). "Further research confirmed SLC39A5 as one of the top three genes contributing to nonsyndromic high myopia." (PMID 34302427, 2021). "Variants in LRPAP1, CTSH, LEPREL1, ZNF644, SLC39A5, and SCO2 genes were comprehensively screened in 298 families with early-onset high myopia." (PMID 30245926, 2018). "Moreover, it points out that multiple associated ribosomal deficits might play a role in DBA-related phenotypes, considering the simultaneous deletion of three of them in the index case (RPS26, PA2G4 and RPL41), and it confirms the association among SLC39A5 functional disruption and severe myopia." (PMID 30524470, 2018). "We screened for mutations in SLC39A5, LEPREL1 and LRPAP1 in a cohort of 187 high myopia patients with Sanger sequencing." (PMID 28442722, 2017). "Based on previous reports, we proposed that SLC39A5, LEPREL1 and LRPAP1were more likely to associate with Chinese high myopia patients." (PMID 28442722, 2017). "According to this hypothesis, the SLC39A5‐induced zinc deficiency suppresses TGF‐β signalling, leading to insufficient ECM synthesis, which may ultimately contribute to high myopia development." (PMID 34302427, 2021). "Therefore, we screened mutations in the three HM associated genes, SLC39A5, LEPREL1 and LRPAP1, and discovered additional mutations in a group of 187 unrelated Chinese patients with high myopia." (PMID 28442722, 2017). "SLC39A5, LEPREL1 and LRPAP1 were more likely to associate with Chinese high myopia patients." (PMID 28442722, 2017). "Further functional studies are needed to elucidate the molecular mechanism of high myopia as related to SLC39A5, however, our results may provided additional genetic evidence for potential contribution of SLC39A5in high myopia." (PMID 28442722, 2017). "However, the mechanisms by which SLC39A5 contributes to high myopia are not well understood." (PMID 34302427, 2021). "In addition to the novel mutations found in five known myopia genes (ADAMTS18, CSMD1, P3H2, RPGR, and SLC39A5), we also identified pathogenic variants in seven ocular disease genes (ABCA4, CEP290, HSPG2, PCDH15, SAG, SEMA4A, and USH2A) as novel candidate genes." (PMID 30245926, 2018). "In order to expand the mutation spectrum of the causative genes in Chinese adult population, we investigated three genes, SLC39A5, LEPREL1 and LRPAP1, in a cohort of 187 independent Chinese patients with high myopia." (PMID 28442722, 2017).
Zinc deficiency (6 papers, 2013 to 2022). A deficiency of the essential metal Zinc; an essential cofactor for many enzymes. "SLC39A5 depletion–induced zinc deficiency directly destabilized Smad proteins, and Smads instability further impaired TGF‐β signalling–mediated ECM synthesis, thus contributing to the pathogenesis of high myopia." (PMID 34302427, 2021). "Overall, the SLC39A5 depletion–induced zinc deficiency destabilized Smad proteins, which inhibited the TGF‐β signalling and downstream ECM synthesis, thus contributing to the pathogenesis of high myopia." (PMID 34302427, 2021). "We found that Smad proteins were rapidly degraded during SLC39A5 deletion–induced zinc deficiency." (PMID 34302427, 2021).
esophageal cancer (5 papers, 2017 to 2025). A primary or metastatic malignant neoplasm involving the esophagus. "For example, SLC39A5 was elevated in human esophageal cancer, and its depletion inhibited esophageal cancer cell growth." (PMID 40992658, 2025).
diabetes (4 papers, 2019 to 2025). "In a GWAS study of the Taiwan Biobank (TWB), four novel genes—NABP2, RASA2, RNF41, and SLC39A5—were identified for human height, and it was also discovered that these genes have associated with cardiovascular disease, diabetes, and cancer." (PMID 39910149, 2025). "A deficiency in SLC39A5 weakens glucose sensitivity and reduces insulin secretion, indicating that SLC39A5 has potential as a therapeutic target for diabetes-related metabolic diseases." (PMID 39850557, 2024). "Next, we examined the role of Slc39a5 in the pathogenesis of HFD-induced diabetes by feeding 6-week-old Slc39a5fl/fl and CKO mice with a high-fat diet containing 60% of calories derived from fat." (PMID 30324491, 2019). "The expression of Slc39a5 was significantly reduced in all three obese and diabetes murine models, which suggests that the leptin signaling does not directly regulate Slc39a5 expression." (PMID 30324491, 2019).
Obesity (2 papers, 2019 to 2024). Accumulation of substantial excess body fat. "Here, we screened 14 genes that encode Slc39a family members and identified Slc39a5 as the sole gene down-regulated in three mouse models of obesity." (PMID 30324491, 2019). "Nonetheless, given the connection with protective effects arising from heterozygous loss of SLC39A5 in humans, we examined the effect of loss of Slc39a5 in mice under conditions of metabolic stress, employing models of congenital or diet-induced obesity, and NASH." (PMID 39671241, 2024). "To assess whether disruption of Slc39a5 function improves glycemic traits in mice, we challenged the Slc39a5-/- mice with well-established models of congenital (leptin-receptor deficiency; Lepr-/- mice) or diet-induced obesity." (PMID 39671241, 2024). "Next, we examined whether loss of Slc39a5 improves liver function in diet-induced obesity." (PMID 39671241, 2024). "Slc39a5-/- mice display improved liver function and reduced hyperglycemia when challenged with congenital or diet-induced obesity." (PMID 39671241, 2024). "The improvements in liver function and steatosis in congenital and diet-induced obesity mouse models lacking Slc39a5, led us to investigate whether loss of Slc39a5 protects against NASH." (PMID 39671241, 2024). "The importance of hepatic zinc in the protective effects against obesity and NASH is further supported by our findings that elevated hepatic zinc in Slc39a5-/- mice enhanced hepatic AMPK and hepatic AKT signaling." (PMID 39671241, 2024).
bladder cancer (1 paper, 2025). "For example, a pan-cancer TCGA analysis found that tumor overexpression of SLC39A3, SLC39A5, and SLC39A11 was associated with better overall survival after bladder cancer diagnosis, whereas tumor overexpression of SLC39A2, SLC39A8, SLC39A9, and SLC39A14 was associated with poorer survival." (PMID 39789109, 2025).
celiac disease (1 paper, 2024). An autoimmune genetic disorder with an unknown pattern of inheritance that primarily affects the digestive tract. "In addition, the promoter regions of Carboxylesterase 1 (CES1), alpha-2-macroglobulin like 1 (A2ML1) and Solute Carrier Family 39 Member 5 (SLC39A5) were significantly hypermethylated in celiac disease." (PMID 38780872, 2024).
fibrosis (1 paper, 2024). the formation of excess fibrous connective tissue in an organ or tissue in a reparative or reactive process. "NAFLD activity score and steatosis-activity-fibrosis score (sum of NAFLD activity score and fibrosis score) were significantly reduced in female NASH Slc39a5-/- mice, but not in their male counterparts." (PMID 39671241, 2024).
Glucose intolerance (1 paper, 2024). Glucose intolerance (GI) can be defined as dysglycemia that comprises both prediabetes and diabetes. "Given that NAFLD and T2D are concurrent comorbidities characterized by hepatic steatosis, glucose intolerance, and insulin resistance, we explored whether loss of Slc39a5 and consequent hepatic zinc accumulation influenced liver function in models of congenital obesity and diet-induced obesity." (PMID 39671241, 2024).
Hepatic steatosis (1 paper, 2024). Steatosis is a term used to denote lipid accumulation within hepatocytes. "However, NASH Slc39a5-/- mice were not protected from hepatic steatosis or hepatocyte hypertrophy." (PMID 39671241, 2024).
Insulin resistance (1 paper, 2024). Increased resistance towards insulin, that is, diminished effectiveness of insulin in reducing blood glucose levels. "Consistently, loss of Slc39a5 resulted in reduced insulin resistance in these models." (PMID 39671241, 2024).
ischaemia (1 paper, 2020). "In addition, we generated two separate slc39a5 knockout lines using CRISPR/Cas9 and found that the resulting phenotype is similar to the slc39a5 morphants, confirming that both cardiac ischaemia and blood accumulation in the CVP are due to the loss of Slc39a5." (PMID 33081634, 2020). "Our finding that slc39a5 morphant embryos develop a clear phenotype that includes cardiac ischaemia and the accumulation of blood in the CVP suggests the possibility of toxicity and/or an off-target effect of the morpholino." (PMID 33081634, 2020).
liver fibrosis (1 paper, 2024). "Diet-induced NASH significantly increased serum ALT and AST levels, body weight, fasting blood glucose, and liver fibrosis in Slc39a5+/+ mice." (PMID 39671241, 2024).
lung adenocarcinoma (1 paper, 2025). A carcinoma that arises from the lung and is characterized by the presence of malignant glandular epithelial cells. "It has also been shown that SLC39A5-induced lung adenocarcinoma cell proliferation suppresses apoptosis via the PI3K–AKT signaling pathways." (PMID 40992658, 2025).
non-alcoholic fatty liver disease (1 paper, 2024). "Taken together, these results suggest SLC39A5 as a potential therapeutic target for non-alcoholic fatty liver disease (NAFLD) due to metabolic derangements including T2D." (PMID 39671241, 2024).
non-alcoholic steatohepatitis (1 paper, 2024). "Loss of Slc39a5 improves hepatic inflammation and fibrosis in female mice challenged with diet-induced non-alcoholic steatohepatitis (NASH)." (PMID 39671241, 2024). "Furthermore, under conditions of diet-induced non-alcoholic steatohepatitis (NASH), Slc39a5-/- mice display significantly attenuated fibrosis and inflammation." (PMID 39671241, 2024).
steatosis (1 paper, 2024). Increased lipid within the cytoplasm of cells. "Loss of Slc39a5 improves liver function and steatosis in leptin-receptor deficient female mice and in female mice challenged with high-fat high fructose diet (HFFD)." (PMID 39671241, 2024). "Moreover, Slc39a5-/-; Lepr-/- mice displayed reduced NAFLD activity score (an aggregate score of macrovesicular steatosis, hepatocellular hypertrophy, and inflammation)." (PMID 39671241, 2024).
type II diabetes (1 paper, 2024). "Rare putative LOF (pLOF) variants in SLC39A5 are associated with elevated serum zinc and nominal protection against type II diabetes (T2D)." (PMID 39671241, 2024).
cancer (9 papers, 2020 to 2025). A tumor composed of atypical neoplastic, often pleomorphic cells that invade other tissues. "Previous studies have documented that SLC39A5 is key in modulating these vital biological processes and various diseases, including several cancers." (PMID 40992658, 2025). "Thus, elucidating the role of SLC39A5 in Zn2+ transport in GC may provide critical insights into its potential contribution to cancer development and progression." (PMID 40992658, 2025). "Besides, the SLC39A5, encoding a zinc transporter, is crucial to the maintenance of TME homeostasis because zinc is a critical component of many enzymes involved in hypoxia, angiogenesis, cell proliferation, and cancer metastasis." (PMID 32149116, 2020). "The roles of SLC39A5, UGT2A3 and SLC17A4 are relatively undescribed in cancer." (PMID 39556603, 2024).
tumor (9 papers, 2019 to 2025). "The knockdown of SLC39A5 alone inhibited tumor growth of nude mice, whereas OE of BATF promoted tumor growth, mitigating the effects of SLC39A5 knockdown." (PMID 40992658, 2025). "Tumor fragments derived from subcutaneous xenografts established using HGC-27 cells with SLC39A5 knockdown alone or in combination with BATF OE." (PMID 40992658, 2025). "BATF overexpression reversed the inhibitory effect of SLC39A5 depletion on the behavior of GC cells and tumor growth." (PMID 40992658, 2025). "Lastly, we observed an inverse relationship between the expression of PTPRN2, LAT and SLC39A5 genes and HR of tumour recurrence from the TCGA PRAD dataset." (PMID 31221986, 2019). "Moreover, elevated expression of SLC39A5 was positively correlated with the advanced tumor node metastasis stage in GC patients." (PMID 40992658, 2025). "In addition, we exhibited that the knockdown of SLC39A5 attenuated GC cell proliferation, migration, and invasion in vitro well as GC tumor growth in vivo." (PMID 40992658, 2025). "SLC39A5, a membrane transporter responsible for the dynamic balance of zinc, was upregulated in LUAD tissues compared with adjacent non-tumor lung tissues, and higher expression of SLC39A5 predicted poor survival in LUAD patients." (PMID 34977043, 2021). "It is noteworthy that the SLC39A2, SLC39A3, SLC39A3, and SLC39A5 showed a significant negative correlation with the macrophages and neutrophil cell infiltration in most tumor types." (PMID 34925450, 2021).
SLC39A5 also shares sentences with these, for which no sentence is quoted: acute pancreatitis (2 papers); esophageal squamous cell carcinoma (2); infection (2); pancreatitis (2); cardiovascular disease (1); Cirrhosis (1); co-infection (1); gastric adenocarcinoma (1); gastric cancer (1); gastric tumor (1); Hyperglycemia (1); iron deficiency (1); liver cancer (1); liver cirrhosis (1); metabolic disease (1); neuroblastoma (1); osteosarcoma (1); ovarian carcinoma (1); serous ovarian cancer (1).